BCLAF3 (BCLAF1 and THRAP3 family member 3)
Description:
Component of the spliceosome complex, important for maintaining embryonic stem cell (ESC) fate. May also be involved in the negative regulation of Wnt-driven stem cell-dependent epithelial renewal in the gastric mucosa.
Synonyms: TOBF1; CXorf23
Tractability: PROTAC: UniProt records ubiquitination sites on it.
Gene: Protein-coding gene on chromosome X (19,912,860 to 19,991,097, reverse strand). Ensembl gene ENSG00000173681.
Subcellular location: Nucleus; Nucleus speckle
Subcellular location (Human Protein Atlas): Nucleoplasm
Gene Ontology:
Molecular function: DNA binding; transcription coregulator activity
Biological process: positive regulation of transcription by RNA polymerase II; alternative mRNA splicing, via spliceosome; positive regulation of stem cell population maintenance
Cellular component: mediator complex; nuclear speck; nucleus; spliceosomal complex
Homologues: Orthologues: chimpanzee BCLAF3 (96% identical), macaque BCLAF3 (95% identical), pig BCLAF3 (81% identical), dog BCLAF3 (78% identical), guinea pig BCLAF3 (74% identical), rat Bclaf3 (65% identical), rabbit BCLAF3 (64% identical), mouse Bclaf3 (64% identical), tropical clawed frog bclaf3 (30% identical), zebrafish zgc:112982 (8% identical). Paralogues in human: THRAP3 (22% identical), BCLAF1 (21% identical).
Diseases named in the same sentence as BCLAF3 in open-access papers:
BCLAF3 is named in the same sentence as 2 diseases in open-access papers, as found by Europe PMC text mining. Sharing a sentence is not in itself a finding about the gene and the disease.
BCLAF3 shares sentences with these, for which no sentence is quoted: epilepsy (1 paper); neurodevelopmental disorder (1).